RPL13AP23 (ribosomal protein L13a pseudogene 23)
Gene: Transcribed processed pseudogene on chromosome 12 (57,674,665 to 57,675,250, forward strand). Ensembl gene ENSG00000242990.
Diseases named in the same sentence as RPL13AP23 in open-access papers:
RPL13AP23 is named in the same sentence as 1 disease in open-access papers, as found by Europe PMC text mining. Sharing a sentence is not in itself a finding about the gene and the disease.
RPL13AP23 shares sentences with these, for which no sentence is quoted: ovarian carcinoma (1 paper).